C22orf31 (chromosome 22 open reading frame 31)
Synonyms: HS747E2A; bK747E2.1
Tractability: PROTAC: ubiquitination databases record sites on it.
Gene: Protein-coding gene on chromosome 22 (29,058,672 to 29,061,831, reverse strand). Ensembl gene ENSG00000100249.
Subcellular location (Human Protein Atlas): Nuclear membrane; Cytosol
Genetic constraint (gnomAD): Loss-of-function variants: 15 observed, 15.98 expected, observed/expected ratio (o/e) 0.94, 90% interval 0.63 to 1.44. The upper end of that interval is the gene's LOEUF score, 1.44, which puts it in group 5 of 6, group 1 being the genes least tolerant of losing a copy. Missense variants: 340 observed, 366.66 expected, observed/expected ratio (o/e) 0.93, 90% interval 0.85 to 1.01. Synonymous variants: 132 observed, 140.85 expected, observed/expected ratio (o/e) 0.94, 90% interval 0.81 to 1.08.
Homologues: Orthologues: chimpanzee C22H22orf31 (99% identical), macaque C10H22orf31 (96% identical), pig C22orf31 (78% identical), dog C22orf31 (77% identical), rabbit C22orf31 (74% identical).